HSD11B1L (hydroxysteroid 11-beta dehydrogenase 1 like)
Description:
Unidirectional NADP(+)-dependent cortisol dehydrogenase (in vitro).
Synonyms: 11-DH3; 11-beta-HSD3; HSD3; SCDR10B; SDR26C2; SCDR10; HSD1L
Tractability: Antibody: UniProt places it where antibodies can reach, with high confidence; UniProt predicts a signal peptide or a membrane-spanning region; its Gene Ontology location is reachable by antibodies, with medium confidence.
Gene: Protein-coding gene on chromosome 19 (5,680,604 to 5,688,524, forward strand). Ensembl gene ENSG00000167733.
Subcellular location: Secreted
Subcellular location (Human Protein Atlas): Vesicles; Predicted to be secreted
Gene Ontology:
Molecular function: cortisol dehydrogenase (NADP+) activity; oxidoreductase activity
Cellular component: extracellular region
Genetic constraint (gnomAD): Loss-of-function variants: 25 observed, 24.35 expected, observed/expected ratio (o/e) 1.03, 90% interval 0.75 to 1.43. The synonymous counts are far from expectation, so gnomAD's model fits this gene poorly and the ratio says little. Missense variants: 372 observed, 323.82 expected, observed/expected ratio (o/e) 1.15, 90% interval 1.05 to 1.25. Synonymous variants: 187 observed, 146.69 expected, observed/expected ratio (o/e) 1.27, 90% interval 1.13 to 1.44.
Homologues: Orthologues: chimpanzee HSD11B1L (100% identical), macaque HSD11B1L (98% identical), pig HSD11B1L (91% identical), dog HSD11B1L (76% identical), zebrafish hsd11b1la (49% identical), tropical clawed frog hsd11b1l (49% identical), zebrafish hsd11b1lb (45% identical), Drosophila melanogaster CG31546 (23% identical), Drosophila melanogaster CG7601 (21% identical), Drosophila melanogaster CG31548 (21% identical), Caenorhabditis elegans T25G12.13 (20% identical), Caenorhabditis elegans dhs-30 (19% identical), and 7 more. Paralogues in human: HSD11B1 (44% identical), DHRS7 (23% identical), DHRS7B (22% identical), RDH8 (22% identical), DHRS7C (21% identical), DHRS11 (20% identical), DHRS4 (20% identical), DHRS2 (18% identical), CBR1 (17% identical), CBR3 (17% identical), DHRS4L2 (16% identical), HSDL2 (15% identical), and 1 more.
Diseases named in the same sentence as HSD11B1L in open-access papers:
HSD11B1L is named in the same sentence as 2 diseases in open-access papers, as found by Europe PMC text mining. Sharing a sentence is not in itself a finding about the gene and the disease. The quoted sentences say what the papers report.
tumour (1 paper, 2025). "Furthermore, pathways involved in xenobiotic metabolism (GSTs, DHDH, AKR7A2, HSD11B1L, CYP1B1, UGTs), drug metabolism, nucleotide metabolism, and homologous recombination (RAD51) reflect the tumour’s ability to adapt to environmental stressors and resist therapy." (PMID 41007296, 2025).
HSD11B1L also shares sentences with these, for which no sentence is quoted: glioblastoma (1 paper).